VHL (von Hippel-Lindau tumor suppressor)
Diseases named in the same sentence as VHL in open-access papers (continued):
Sharing a sentence is not in itself a finding about the gene and the disease.
renal cell carcinoma (continued). "From renal cell carcinoma (RCC), it is known that chromosome 3 loss leads to VHL inactivation, and a subsequent increase in HIF1a." (PMID 31323773, 2019). "Indeed, VHL loss-of-function mutations are found in up to 90% of all renal cell carcinomas." (PMID 29772792, 2018). "Clear cell renal cell carcinoma (ccRCC) is the most common subtype of renal cell carcinoma (RCC), and is frequently accompanied by the genetic features of von Hippel–Lindau (VHL) loss." (PMID 29527128, 2018). "The clear cell histological variant is the most common manifestation of renal cell carcinoma and has a pathology that is unique among other RCC subtypes in its association with the mutated von Hippel Lindau (VHL) tumour suppressor gene." (PMID 29980758, 2018). "The von Hippel-Lindau (VHL) gene is often inactivated in sporadic renal cell carcinoma (RCC) by mutation or promoter hypermethylation." (PMID 28103578, 2017). "Renal cell carcinoma (RCC) most commonly arises from the loss of the von Hippel–Lindau (VHL) tumor suppressor gene and has the highest death rate among solid urological tumors." (PMID 29051480, 2017). "A striking example is the activation of HIF by inactivating mutations of the VHL tumour suppressor, which is observed in renal cell carcinoma (RCC), which leads to high level activation of HIF irrespective of other considerations." (PMID 28315322, 2017). "The most common VHL-associated tumors are hemangioblastomas involving brain, spinal cord, and retina; clear cell renal cell carcinoma (RCC); pheochromocytomas and paragangliomas; and pancreatic neuroendocrine tumors (PNETs)." (PMID 28785532, 2017). "Mutational inactivation of the VHL tumor suppressor plays key roles in the development of renal cell carcinoma (RCC), and mutated VHL-mediated VEGF induction has become the main target for the current RCC therapy." (PMID 26304926, 2015). "The commonest histological type of renal cancer, clear cell renal cell carcinoma (cc RCC), is associated with genetic and epigenetic changes in the von Hippel-Lindau (VHL) tumour suppressor." (PMID 20964835, 2010). "Metastatic renal cell carcinoma (RCC) remains the leading cause of mortality in patients with clear cell RCC arising from mutations in the von Hippel Lindau (VHL) tumor suppressor." (PMID 17140440, 2006). "RESULTS: The most common treatment observed in the VHL-CNS-Hb cohort (N = 220) was targeted therapy for renal cell carcinoma (2.34 treatment events per 10 person-years)." (PMID 42010687, 2026). "This stabilized HIF-α activates the transcription of proangiogenic factors and cell cycle regulators, driving the pathogenesis of VHL-associated neoplasms such as renal cell carcinoma (RCC), central nervous system (CNS) haemangioblastomas, and pancreatic neuroendocrine tumours." (PMID 41294695, 2025). "The VEF captures the following VHL-related tumors: retinal hemangioblastoma, CNS hemangioblastoma, renal cell carcinoma, pheochromocytoma, pancreatic neuroendocrine tumor, endolymphatic sac tumor, and paraganglioma." (PMID 40647474, 2025). "For example, mutations in the VHL gene, which destabilize HIF-1α, are common in renal cell carcinoma and drive hypoxia-associated phenotypes." (PMID 39981236, 2025). "VHL is broadly essential for cell proliferation, yet it is a key tumor suppressor in renal cell carcinoma." (PMID 41420106, 2025). "Furthermore, von Hippel-Lindau-associated kidney cancer (VHL-RCC) and sporadic clear cell renal cell carcinoma (s-RCC) cells cluster with glomerular/vascular cells, suggesting a glomerular/vascular origin for VHL-RCC and s-RCC." (PMID 41035074, 2025). "The tumor suppressor gene VHL is involved in the development of renal tumors, and early VHL tumor suppressor gene inactivation is present in over 60% of sporadic renal cell carcinomas." (PMID 40225869, 2025).
renal cell carcinoma (continued). "Among the eight patients with VHL who underwent WB-MRI, one was diagnosed with cancer (renal cell carcinoma; cancer detection rate of 13%) and received treatment with curative intent." (PMID 40138602, 2025). "As the main type of renal cell carcinoma (RCC), clear cell RCC (ccRCC) is often associated with the deletion or mutation of the von Hippel Lindau (VHL) gene, enhancement of glucose and lipid metabolism, and heterogeneity of the tumor microenvironment." (PMID 39399506, 2024). "Overall, our findings underscore VHL’s crucial role in ccRCC by regulating m6A modification and RNA stability, potentially impacting renal cell carcinoma development and progression." (PMID 38618952, 2024). "To further confirm the tumor growth suppressive function of ANGPTL4, we generated Renca mouse renal cell carcinoma cells with WT VHL, which express V5-tagged ANGPTL4 (Renca-A4)." (PMID 39105498, 2024). "Belzutifan, an HIF2a inhibitor, has recently been approved by the United States Food and Drug Administration for use in VHL, especially renal cell carcinoma, CNS hemangioblastomas, or pancreatic neuroendocrine tumors, not requiring immediate surgery." (PMID 38975461, 2024). "Emerging biomarkers such as gene expression profiles and the loss of pro-angiogenic proteins VHL and PBRM-1 show promise for identifying renal cell carcinoma cases likely to respond to ICI." (PMID 37568390, 2023). "The VHL gene has been found to be silenced by methylation in 20%–30% of individuals with renal cell carcinoma, acute myeloid leukemia, or multiple myeloma while in plasma cell neoplasia methylation of the VHL promoter is a common event." (PMID 36036061, 2023). "The abnormal condition of VHL, HIF, MDM2, MDM4, and other genes linked to the development of renal cell carcinoma is closely related to the disappearance of its anticancer function." (PMID 37861516, 2023). "We also have to mention that the pathophysiology of renal cell carcinoma is mainly based on the von Hippel-Lindau/hypoxia-inducible factor 1-α (VHL/HIF) signaling pathway." (PMID 37764501, 2023). "We showed that FOXA2 activates HIF2α expression to promote renal cell carcinoma progression and is regulated by VHL." (PMID 38072043, 2023). "In renal cell carcinoma, HIF signaling is even more essential due to the frequent inactivation mutation of von Hippel‒Lindau (VHL) in sporadic cases." (PMID 37596681, 2023). "NPT-BEZ235 also reduced tumor burden in a mouse xenograft model of VHL-null renal cell carcinoma (RCC)." (PMID 37780208, 2023). "In ccRCC, due to the loss of VHL and the constitutive activation of HIF1, CAIX is also constitutively expressed, while other renal cell cancers such as chromophobe RCC and papillary RCC are typically CAIX negative." (PMID 38139136, 2023). "The proliferation and apoptosis of cells were measured to clarify the inhibitory effect of the VHL gene in renal cell carcinoma." (PMID 35035522, 2022). "Efficacy of belzutifan was established by NCT 03401788, which was an open-label clinical trial for patients with renal cell carcinoma and a VHL germline alteration." (PMID 35819008, 2022). "In addition, we find that YAP1 nuclear localization is markedly elevated in renal cell carcinoma (RCC), along with its association with HIF1α; this is significant, because VHL is often mutated and is a well-known tumor suppressor in RCC." (PMID 35937460, 2022). "Von Hippel-Lindau (VHL) genes are intimately involved in renal cell carcinoma (RCC), including clear cell RCC (ccRCC) pathogenesis." (PMID 35448166, 2022). "The inactivating mutations in the Von Hippel-Lindau (VHL) tumor suppressor factor led to stabilization of HIF-1ɑ and HIF-2ɑ factors, which is often associated with the development of renal cell carcinomas." (PMID 36139404, 2022). "Among patients with VHL, the presence of extracranial tumors was also reported, of which renal cell carcinoma is the most common, followed by adrenal pheochromocytoma." (PMID 36760665, 2022).
renal cell carcinoma (continued). "In this paper, we study the role of the VHL gene in regulating the proliferation and apoptosis of renal cell carcinoma, as well as the safety and transfection efficiency of ultrasound microbubble gene transfection technology." (PMID 35035522, 2022). "Next, a panel of VHL-null renal cell carcinoma (RCC) cell lines with elevated AURKA expression were used to determine if NVP-BEZ235 treatment decreased AURKA expression." (PMID 34002003, 2021). "The most common type of renal cell carcinoma (ccRCC) is characterized by inactivation of VHL leading to HIF stabilization and increased transcription of HIF target genes." (PMID 33540838, 2021). "VHL functions as a tumor suppressor gene in some tumors, such as renal cell carcinoma and pheochromocytoma, but few studies have reported its role in GC." (PMID 34594359, 2021). "Renal cell carcinoma, one of the most common urological malignancies, is characterized by frequent inactivation of the VHL gene and hyperactivation of the HIF-VEGF axis, leading to abundant vascularization within tumors." (PMID 34030133, 2021). "Verrucarin induces apoptosis in the cell by blocking translation in its early stages.VHL in the structure of SGs interferes with apoptosis in renal cell carcinoma cells by interfering with the verrucarin-induced apoptotic process." (PMID 35004322, 2021). "In another cancer-directed study, Cadherin 1 has been shown to regulate VHL in a cell cycle-dependent manner in renal cell carcinoma cells." (PMID 34209205, 2021). "Specific direct interaction of HIF2α (but not HIF1α or HIF3α) with eIF3e led to HIF2α degradation via the proteasome pathway in a hypoxia- and VHL-independent manner in renal cell carcinoma 786-O cells." (PMID 34209205, 2021). "Clear cell renal cell carcinoma (ccRCC), the most prevalent subtype of renal cell carcinoma (RCC), is characterized by VHL mutations in 70–80% of cases, high metastasis rate and mortality, and resistance to radiotherapy and chemotherapy." (PMID 32814829, 2020). "Total serum ctDNA levels and CpG island methylation of RASSF1A and VHL were shown to support the diagnosis of renal cell carcinoma (RCC) and VHL methylation indicates clear cell RCC." (PMID 32010431, 2020). "As a reference, the SK-RC-52 renal cell carcinoma model, which constitutively overexpresses CAIX due to the VHL mutation, had a much higher CAIX positive fraction of 0.59 ± 0.15 (compared to SCCNij153 p = 0.03)." (PMID 31827111, 2019). "Renal cell carcinoma and pancreatic neuroendocrine tumors were seen in 37 of 191 patients (19%) with VHL." (PMID 31397861, 2019). "We demonstrated that 15d-PGJ2 enhanced anticancer activities independently of VHL status in renal cell carcinomas." (PMID 30815591, 2019). "We therefore first performed western blotting for FANCD2 in VHL-deficient and VHLWT-complemented 786-O renal cell carcinoma cells after exposure to normoxia or hypoxia (<0.01% O2) for 24 and 48 h." (PMID 29435132, 2018). "Clear cell renal cell carcinoma (ccRCC), which accounts for approximately 75% of cases of renal cell carcinoma (RCC), is characterized in up to 83% of cases by mutations of the Von Hippel-Lindau (VHL) gene." (PMID 29732003, 2018). "In previous studies, we found that 2'-hydroxyflavonone (2HF), a citrus flavonoid, inhibits the growth of renal cell carcinoma in a VHL-dependent manner." (PMID 30546837, 2018). "In this study, we investigated the effects of long-term hypoxia in 786-O, a VHL-defective renal cell carcinoma cell line, to identify potential genes and microRNAs associated with tumor malignancy." (PMID 29215599, 2017). "The high rate of somatic VHL mutations in sporadic kidney cancers, particularly clear cell renal cell carcinomas (ccRCC) suggests that inactivation of the VHL protein plays a critical role in the initiation of RCC in the general population." (PMID 27682873, 2017).
renal cell carcinoma (continued). "A representative example is renal cell carcinoma (RCC), in which HIF is highly expressed due to frequent mutations of the von Hippel-Lindau (VHL) gene." (PMID 28476028, 2017). "The Von Hippel Lindau disease is a hereditary neoplastic syndrome caused by mutations in the VHL tumour suppressor gene, which are responsible for a predisposition to renal cell carcinoma (RCC), retinal or central nervous system hemangioblastomas, pancreatic cysts, and PCCs." (PMID 28471419, 2017). "We conducted this study to investigate the long-term effects of hypoxia in 786-O, a VHL-defective renal cell carcinoma cell line, to identify potential genes and microRNAs associated with tumor malignancy using NGS and bioinformatics." (PMID 29215599, 2017). "Un-physiological activation of hypoxia inducible factor (HIF) is an early event in most renal cell cancers (RCC) following inactivation of the von Hippel-Lindau tumor suppressor." (PMID 28715484, 2017). "Germline mutations of VHL account for more than 95% of the patients affected by VHL (5% have somatic inactivation of the VHL gene in sporadically occurring hemangioblastomas and renal cell carcinomas)." (PMID 27446927, 2016). "In contrast, studies in VHL-related renal cell carcinoma and retinal hemangioblastoma high levels of CXCR4 and VEGF, and not CXCL12, were found." (PMID 26920352, 2016). "In both conditions, renal cell carcinoma (RCC) cells devoid of VHL expression showed higher resistance to NDV killing." (PMID 27902314, 2016). "Type 2 VHL disease shows a high risk of pheochromocytoma (PCC) and germ line missense mutations is subdivided into high risk (2B), low risk (2A), or absence (2C) of Renal cell carcinoma (RCC) and heamangioblastoma is correlated with function of pVHL to impair HIF-1α activity." (PMID 26503325, 2015). "The elucidation of the VHL-HIF-1α(hypoxia inducible factor-1α)-VEGF (vascular endothelial growth factor) pathway has led to the development of targeted therapy in renal cell carcinoma (RCC)." (PMID 26021863, 2015). "We then tested the cellular inhibition of 1 and IOX4 using a von Hippel-Lindau (VHL)-defective human renal cell carcinoma (RCC4) cell line, in which HIFα proteins are constitutively stabilized." (PMID 26147748, 2015). "Inactivating mutations in VHL lead to HIF stabilisation in normoxia and are often found in renal cell carcinoma (RCC)." (PMID 25700172, 2015). "We now further analyzed the PHD3-depletion induced cell cycle arrest using synchronized HeLa cells and renal cell adenocarcinoma cells (786-O), the latter bearing VHL inactivation and high basal PHD3 expression." (PMID 26223520, 2015). "In the presence of a positive family history, VHL can be diagnosed clinically in a patient with at least one typical VHL tumor, such as retinal or CNS HB, renal cell carcinoma, pheochromocytoma or pancreatic tumor." (PMID 28326249, 2014). "Several studies suggest that VHL plays a critical role in regulating apoptotic pathways in renal cell carcinoma." (PMID 25490036, 2014). "VHL gene is silenced by methylation in 20–30% of patients with renal cell carcinoma and other tumor types such as multiple myeloma (30%)." (PMID 25490036, 2014). "A similar role for VHL, another renal tumor suppressor, in the regulation of autophagic events in renal cell carcinomas has been recently described." (PMID 24763318, 2014). "Finding reliance on glutaminolysis in VHL-mutant renal cell carcinoma was of particular significance, given the generally predominant dependence of tumors on glycolysis." (PMID 23940778, 2013). "Other VHL targets have been identified in renal cell carcinoma cell lines; interestingly, several are downregulated by VHL." (PMID 23976881, 2013). "This may have relevance to the development of renal cell carcinoma (RCC), where mutations of the von Hippel-Lindau (VHL) gene are major risk factors for the development of familial and sporadic RCC." (PMID 23305401, 2013).
renal cell carcinoma (continued). "Targets of Hsa-miR-200b-3p were involved in several pathways like renal cell carcinoma, associated to some oncogenes such as MET, or tumors suppressors like VHL, FH and BHD." (PMID 23372853, 2013). "Pathway analyses provided corroborative evidence for differential regulation of molecular and cellular functions influencing cancer energetics, metabolism and cell proliferation in renal cell carcinoma with distinct VHL genotype." (PMID 23940778, 2013). "Craven compared the mitochondrial proteome in VHL (von Hippel Lindau, a tumor suppressor gene)-defective RCCs (renal cell carcinomas), which were transfected with either a control vector or wild-type VHL." (PMID 22424240, 2012). "Whether sporadic renal cell carcinoma (RCC) prognosis is related to the type of VHL mutation or altered expression is unclear." (PMID 23202921, 2012). "Of these, BRK1:VHL represents the fusion of two genes that have previously been shown to co-operate in the development of renal cell carcinoma." (PMID 22761941, 2012). "These agents are thought to work through a mechanism influencing the involvement of the tumor-suppressor VHL gene in the pathogenesis of rcc." (PMID 19478895, 2009). "Renal cell carcinoma-10 lacks VHL expression, whereas VHL+53 is a transfected revertant for this gene that controls the hypoxia response." (PMID 19277038, 2009). "von Hippel-Lindau disease is characterized by a spectrum of hypervascular tumors, including renal cell carcinoma, hemangioblastoma, and pheochromocytoma, which occur with VHL genotype-specific differences in penetrance." (PMID 19030229, 2008). "Their goal was to identify genes regulated bythe von Hippel-Lindau tumor suppressor protein(pVHL) in renal cell carcinoma cells." (PMID 18779872, 2008). "Renal cell carcinoma cells that have lost VHL tumor suppressor function lose the ability to negatively regulate HIF-2α protein levels, thereby allowing HIF-2α protein to accumulate and dimerize with HIF-β to form a functional transcription factor." (PMID 17140440, 2006). "In renal cell carcinomas, VHL inactivation occurs in most sporadic cases, resulting in an accumulation of CA9, HIF-1α and HIF-2α." (PMID 15558070, 2005). "For example, based on clinical trial data, patients with renal cell carcinoma who have Von Hippel-Lindau tumor suppressor (VHL) alterations may benefit from treatments like sunitinib, sorafenib, bevacizumab, or axitinib." (PMID 41216191, 2025). "Notably, the FDA approval of belzutifan for renal cell carcinoma signifies its promising potential for broader use, extending beyond the VHL patient population." (PMID 41174705, 2025). "None of the individuals demonstrated visceral manifestations of VHL, such as renal cell carcinoma, pheochromocytoma, or pancreatic tumors, which may be attributable to their relatively young age at diagnosis." (PMID 41302074, 2025). "This theory would explain the observed 30% partial response rate of Belzutifan in VHL-associated hemangioblastomas, while this drug and PT2385, a first-generation HIF-2α inhibitor, demonstrated clinical efficacy in VHL patients with renal cell carcinoma (RCC)." (PMID 40427061, 2025). "However, a direct effect of hypoxia on HERVE 6q15 transcription was evident by analysis of RNA-seq data from renal cell carcinoma RCC4 cells with restored expression of the VHL tumour suppressor (GSE120887)." (PMID 40336011, 2025). "Reassuringly, the most enriched pathways were HIF-1 signaling (4.5-fold enrichment, p = 3.18E−17) and renal cell carcinoma (4-fold enrichment, p = 5.65E−09), the latter a disease where the HIF transcriptional response is active due to VHL inactivation by mutation." (PMID 39892389, 2025). "The reason for this could be attributed to the fact that VHL plays a crucial role in the successful assembly of SGs in renal cell carcinoma cells, and a majority of renal cell carcinomas exhibit functional deletion mutations in the VHL gene." (PMID 40546967, 2025).